TCERG1 (transcription elongation regulator 1)
Description:
Transcription factor that binds RNA polymerase II and inhibits the elongation of transcripts from target promoters. Regulates transcription elongation in a TATA box-dependent manner. Necessary for TAT-dependent activation of the human immunodeficiency virus type 1 (HIV-1) promoter.
Synonyms: CA150; TAF2S; Urn1
Tractability: Small molecule: a structure with a bound ligand is known. PROTAC: UniProt records ubiquitination sites on it; ubiquitination databases record sites on it; its protein half-life has been measured.
Gene: Protein-coding gene on chromosome 5 (146,447,311 to 146,511,963, forward strand). Ensembl gene ENSG00000113649.
Subcellular location: Nucleus
Subcellular location (Human Protein Atlas): Nucleoplasm
Pathways (Reactome):
Metabolism of RNA: mRNA Polyadenylation; mRNA Splicing - Major Pathway
Gene Ontology:
Molecular function: identical protein binding; protein binding; RNA binding; RNA polymerase II-specific DNA-binding transcription factor binding; transcription corepressor activity; ubiquitin-like protein conjugating enzyme binding; RNA polymerase binding; transcription coactivator activity; transcription coregulator activity; transcription elongation factor activity
Biological process: mRNA processing; negative regulation of transcription by RNA polymerase II; positive regulation of transcription by RNA polymerase II; RNA splicing; negative regulation of transcription elongation by RNA polymerase II; positive regulation of transcription elongation by RNA polymerase II
Cellular component: nucleoplasm; nuclear speck; nucleus
Genetic constraint (gnomAD): Loss-of-function variants: 28 observed, 118.9 expected, observed/expected ratio (o/e) 0.24, 90% interval 0.17 to 0.32. The upper end of that interval is the gene's LOEUF score, 0.32, which puts it in group 1 of 6, group 1 being the genes least tolerant of losing a copy. Missense variants: 937 observed, 1,313.3 expected, observed/expected ratio (o/e) 0.71, 90% interval 0.68 to 0.75. Synonymous variants: 451 observed, 440.45 expected, observed/expected ratio (o/e) 1.02, 90% interval 0.95 to 1.11.
Homologues: Orthologues: macaque TCERG1 (99% identical), chimpanzee TCERG1 (98% identical), rabbit TCERG1 (97% identical), dog TCERG1 (97% identical), mouse Tcerg1 (96% identical), rat Tcerg1 (94% identical), pig TCERG1 (91% identical), guinea pig TCERG1 (90% identical), tropical clawed frog tcerg1 (76% identical), zebrafish tcerg1a (42% identical). Paralogues in human: TCERG1L (18% identical), ARHGAP5 (15% identical).
Diseases named in the same sentence as TCERG1 in open-access papers:
TCERG1 is named in the same sentence as 29 diseases in open-access papers, as found by Europe PMC text mining. Sharing a sentence is not in itself a finding about the gene and the disease. The quoted sentences say what the papers report.
Huntington disease (4 papers, 2018 to 2025). Huntington disease (HD) is a rare neurodegenerative disorder of the central nervous system characterized by unwanted choreatic movements, behavioral and psychiatric disturbances and dementia. "Interestingly, TCERG1 has already been implicated in the pathogenesis of the neurodegenerative disorder Huntington’s disease (HD)." (PMID 30541625, 2018). "We examined a single nucleotide variant, rs79727797, on chromosome 5 in the TCERG1 gene, previously reported to be associated with Huntington’s disease and a quasi-tandem repeat (QTR) hexamer in exon 4 of TCERG1 with a central pure repeat." (PMID 36064847, 2022). "Interestingly, TCERG1 is involved in the pathogenesis of Huntington’s disease (HD) and plays a neuroprotective role in HD due to its overexpression that can rescue neuronal cell death caused by mutant HTT neurotoxicity." (PMID 36299588, 2022). "For example, our reassessment of modifiers of mHTT toxicity in zQ175 mice showed an overlap with Huntington’s disease modifier genes CCDC82 and TCERG1." (PMID 39801710, 2025).
amyotrophic lateral sclerosis (3 papers, 2019 to 2022). Amyotrophic lateral sclerosis (ALS) is a neurodegenerative disease characterized by progressive muscular paralysis reflecting degeneration of motor neurons in the primary motor cortex, corticospinal tracts, brainstem and spinal cord. "In amyotrophic lateral sclerosis and some cases of frontotemporal dementia, TCERG1 increases the levels of TDP-43, the major constituent of the pathological hallmark inclusions in mammalian cells." (PMID 36064847, 2022). "Further TCERG1 increases the expression of TDP-43 which is involved in Amyotrophic Lateral Sclerosis pathogenesis." (PMID 31805175, 2019).
breast carcinoma (3 papers, 2018 to 2021). "Results from a transcriptomic array indicated a series of newly described transcription factors including HOXB7, MEIS2, TCERG1, and DNAJC2, that were associated to poor outcome in HER2+ breast cancer subtype and downregulated by the MZ1-trastuzumab combination." (PMID 33741018, 2021).
hepatocellular carcinoma (2 papers, 2022 to 2025). A malignant tumor that arises from hepatocytes. "In hepatocellular carcinoma, high TCERG1 expression associates with enhanced cell cycle, migration and invasion, leading to a poor prognosis." (PMID 40038783, 2025). "Next, we used ssGSEA and Spearman correlation analysis to explore the relationship between high TCERG1 expression and immune infiltration level in hepatocellular carcinoma." (PMID 36299588, 2022). "After demonstrating the differential expression of TCERG1 in different immune and molecular subtypes, we explored the potential relationship between TCERG1 expression and immune cell infiltration in hepatocellular carcinoma." (PMID 36299588, 2022). "Next, through the TISIDB website, we explored the role of TCERG1 gene expression in the immune and molecular subtypes of hepatocellular carcinoma." (PMID 36299588, 2022). "The results of RT-qPCR showed that TCERG1 was highly expressed in hepatocellular carcinoma cell lines SNU-449, SMMC-7721, Huh-7 and MHCC97-H compared with normal hepatocytes LO2, and the difference was statistically significant." (PMID 36299588, 2022). "In this study, we analyzed the expression of TCERG1 gene in hepatocellular carcinoma (HCC) patients, its clinical significance, and its possible prognostic value by bioinformatics." (PMID 36299588, 2022). "The specific mechanism for TCERG1 in hepatocellular carcinoma apoptosis has not been reported in detail and needs to be further explored." (PMID 36299588, 2022).
lung carcinoma (2 papers, 2020). "Through our analysis, we also found other eight proteins (ACAT2, PSIP1, TCERG1, DPYSL5, TUBA1A, AKR1B1, ANP32E, and TXNDC17) that have been associated with other cancers, but not in lung cancer." (PMID 32351780, 2020).
adenoma (1 paper, 2015). A neoplasm arising from the epithelium. "Such analyses identified three genes (ACVR2A, TGFBR2, and SLC22A9) and an additional two genes (TCERG1 and TRIM59) whose mutations were enriched for clonal and adenoma-specific categories, respectively." (PMID 26336987, 2015).
diabetes (1 paper, 2020). "Although the involvement of this gene in diabetes and insulin secretion has not been reported, Tcerg1 might indirectly affect insulin secretion through the regulation of insulin secretion related gene expression." (PMID 32502168, 2020).
HIV-1 infection (1 paper, 2013). The type species of lentivirus and the etiologic agent of acquired immunodeficiency syndrome (AIDS). "We report that TCERG1 is required for both basal and Tat-dependent transcriptional activation in cells of the immune system, which are the relevant targets in HIV-1 infection." (PMID 24165037, 2013). "Our experiments with TCERG1 were predominantly performed in Jurkat and PBLs, which are often used to examine transcriptional regulation and HIV-1 infection in lymphocytes, the natural targets of HIV-1." (PMID 24165037, 2013).
liver cancer (1 paper, 2022). An epithelial or non-epithelial malignant neoplasm that arises from the liver. "Logistic regression, GSEA enrichment, TME, and single-sample set gene enrichment analysis (ssGSEA) were performed to explore the effects of TCERG1 on liver cancer biological function and immune infiltrates." (PMID 36299588, 2022). "These suggested that TCERG1 might be involved in immunomodulation and play potential role in the occurrence and development of liver cancer." (PMID 36299588, 2022). "Therefore, this study was conducted to assess the prognostic significance of TCERG1 gene expression in HCC by bioinformatics analysis of clinical features and survival data from The Genome Atlas of Liver Cancer (TCGA-LIHC)." (PMID 36299588, 2022). "At present, the role of TCERG1 gene in cancer has been reported less, but the clinical pathological significance and systematic analysis of TCERG1 gene in liver cancer patients have not been reported." (PMID 36299588, 2022).
liver disease (1 paper, 2022). "With a better understanding of its function, TCERG1 could serve as an effective tool for the diagnosis and treatment of HCC and may help to make biomarker therapy a promising option for the treatment of liver disease in the future." (PMID 36299588, 2022).
proteinopathies (1 paper, 2018). "Therefore, our data suggest the possibility that targeting TCERG1 could be therapeutic in TDP-43 proteinopathies." (PMID 30541625, 2018).
Stroke (1 paper, 2025). Sudden impairment of blood flow to a part of the brain due to occlusion or rupture of an artery to the brain. "Among them, Wnk1 and Tcerg1 were upregulated in DAM and might modulate the maturation of this stroke‐induced microglial subtype." (PMID 39930981, 2025).
cancer (4 papers, 2019 to 2022). A tumor composed of atypical neoplastic, often pleomorphic cells that invade other tissues. "In addition, GSEA enrichment results showed that the high expression phenotype of TCERG1 gene was closely associated with cell cycle, apoptosis, pathway in cancer and other signaling pathways." (PMID 36299588, 2022). "In this study, the expression of TCERG1 in pan-cancer was explored through multiple platforms, and further verified using qRT-PCR, and the results showed that the expression of TCERG1 gene in tumor tissue was increased." (PMID 36299588, 2022). "To explore the role of TCERG1 in the clinical prognosis of HCC patients, we first analyzed the expression of TCERG1 in different cancer types." (PMID 36299588, 2022). "However, the prognostic and immunological role of TCERG1 in human cancer remains unknown." (PMID 36299588, 2022).
infection (3 papers, 2025). The state of being infected such as from the introduction of a foreign agent such as serum, vaccine, antigenic substance or organism. "TCER-1, the C. elegans homolog of mammalian TCERG1, suppresses immunity and promotes fertility, especially upon maternal infection." (PMID 40791391, 2025).
tumor (1 paper, 2022). "Multifactorial analysis showed that high TCERG1 expression was an independent risk factor affecting tumor prognosis." (PMID 36299588, 2022). "High TCERG1 expression level was associated with T stage (p = 0.048), gender (p = 0.039), race (p = 0.042), age (p = 0.001), and weight (p = 0.018), Pathologic stage (p = 0.042) Tumor status (p = 0.007) and histologic grad correlated (p < 0.001)." (PMID 36299588, 2022). "Through spearman correlation analysis, the relationship between the expression level of TCERG1 in the HCC tumor microenvironment and the level of immune cell infiltration by the ssGSEA quorum was determined." (PMID 36299588, 2022). "The expression of TCERG1 was positively correlated with tumor immune infiltrating cells (T helper two cells, T helper cells)." (PMID 36299588, 2022). "The results showed that TCERG1 overexpression was significantly correlated with clinical status, T stage, pathologic stage, histologic grade, tumor status, age, weight, and AFP (ng/ml) (*p < 0.05, **p < 0.01, ***p < 0.001)." (PMID 36299588, 2022). "At the same time, TCERG1 may also become a new target for tumor immunotherapy." (PMID 36299588, 2022). "In addition, immunohistochemical analysis obtained by HPA showed that TCERG1 had higher expression levels in tumor tissues compared to non-tumor tissues, while qRT-PCR further verified that TCERG1 gene was highly expressed in HCC." (PMID 36299588, 2022).
TCERG1 also shares sentences with these, for which no sentence is quoted: colorectal cancer (1 paper); endometrial cancer (1); Fanconi anemia (1); frontotemporal dementia (1); genetic disease (1); immune disease (1); meningitis (1); myelofibrosis (1); neurological disorders (1); oral cancer (1); ovarian carcinoma (1); Parkinson disease (1); post-traumatic stress disorder (1); Prader-Willi syndrome (1).